XIAP (X-linked inhibitor of apoptosis)
Diseases named in the same sentence as XIAP in open-access papers (continued):
Sharing a sentence is not in itself a finding about the gene and the disease.
cancer (continued). "This is largely attributed to the presence of a potent internal ribosomal entry sequence (IRES) in the long 5′ untranslated region (UTR) of XIAP mRNA that controls the translation of XIAP protein in response to physiological, pathological and therapeutic stress in normal and cancer cells." (PMID 34199946, 2021). "Accordingly, both XIAP and cIAPs have become promising targets for cancer therapy." (PMID 34943974, 2021). "Numerous tumors overexpress XIAP and cIAPs, which enables cancer cells to escape apoptosis." (PMID 34943974, 2021). "So, this study focused mainly on computer aided drug design process like structure-based pharmacophore modeling, virtual screening, ADMET, molecular docking and dynamic simulation approaches to identify the possible natural antagonist against XIAP protein to treat the cancer." (PMID 33603068, 2021). "Thus, XIAP represents an attractive target for the development of apoptosis-resistant cancer treatments." (PMID 34199423, 2021). "The down-regulation of anti-apoptotic gene products such as B-cell lymphoma 2 (Bcl-2), X-linked inhibitor of apoptosis (XIAP), inducible nitric oxide synthase (iNOS), and cyclooxygenase-2 (COX-2) may be implicated to mediate the anti-cancer effects." (PMID 34443529, 2021). "Embelin has also been found to be a cell-permeable, small-molecular weight inhibitor of X-linked inhibitor of apoptosis (XIAP), a target of apoptosis-resistance of cancer cells, and could hold great potential in cancer therapy." (PMID 34282169, 2021). "The XIAP transcript has been frequently expressed in different cancers." (PMID 32537125, 2020). "Thus, abnormal expression of XIAP is a useful bio-marker for the early detection of cancer and other diseases (vide supra)." (PMID 33138314, 2020). "Therefore, it is unclear on the reason of having IAPs such as XIAP and survivin as autophagy suppressors, given that upregulation of autophagy and IAPs should both promote the survival of cancer cells, especially under cellular stressful conditions." (PMID 32019552, 2020). "Drugs targeting XIAP for preventing cancer progression have been identified." (PMID 33138314, 2020). "Many tumors over-express XIAP and cIAP1, thereby allowing cancer cells to escape apoptosis." (PMID 32182843, 2020). "Therefore, our findings regarding the reciprocal regulation of OGT and XIAP provide a novel molecular mechanism for controlling cancer growth and invasion regulated by OGT and O-GlcNAc modification." (PMID 32994395, 2020). "Embelin acts as an inhibitor of XIAP in a variety of cancers." (PMID 32106546, 2020). "Thus, our findings reveal a new molecular mechanism regulating OGT and XIAP as key factors in cancer growth and invasion." (PMID 32994395, 2020). "Consequently, the present study was aimed to identify the protein targets regulated by XIAP in the proliferation of cancer cells in MCF-7 cell line." (PMID 32537125, 2020). "While it remains to be elucidated how miR-7-3p enhances the sensitivity of cancer cells to luteolin and silibinin, miR-7-3p is recognized to effectively reduce the level of anti-apoptotic factors, such as BCL-2 and X-linked inhibitor of apoptosis (XIAP)." (PMID 33066509, 2020). "Furthermore, proteome analysis revealed that cancer cell lines with high levels of XIAP were particularly sensitive to the killing effect of A4." (PMID 32587235, 2020). "Therefore, Smac-mimetics can be primarily useful for targeting tumors with high levels of cIAPs, whereas ARTS-mimetics are expected to be effective against cancers with high levels of XIAP." (PMID 32182843, 2020). "Our findings also suggest that protection from tubular cell apoptosis during treatment with cisplatin for cancer may be achieved by upregulation of XIAP and Akt." (PMID 32832155, 2020).
cancer (continued). "This variation in the effectiveness of XIAP to OGT regulation may be a product of the differences in the pool of O-GlcNAc-modified proteins in specific cancer types." (PMID 32994395, 2020). "The regulatory non-coding RNAs are also involved in XIAP regulation during cancer progression." (PMID 33138314, 2020). "It reported that PIM-2 cooperates with XIAP to mediate cancer cells apoptosis." (PMID 32062612, 2020). "Therefore, the exact mechanisms by which XIAP regulates necroptosis in cancer cells merit further investigation." (PMID 32381104, 2020). "Another significant impact of XIAP on cancer biology is to activate NF-κB signal pathway." (PMID 33097010, 2020). "SMs directly bind XIAP, thereby activating caspases and inducing apoptosis of cancer cells." (PMID 32325691, 2020). "Cancer cell lines with high levels of XIAP were particularly sensitive to the killing effect of A4." (PMID 32587235, 2020). "Hence, RNA mimics targeting XIAP are being intensely studied for their potential utilization in cancer therapy." (PMID 33138314, 2020). "This research validated that XIAP was a reliable bio-marker for cancer diagnosis and prognosis." (PMID 33138314, 2020). "XIAP is ubiquitously expressed and its levels are significantly increased in cancer cells." (PMID 31754776, 2020). "Nevertheless, the overall role of XIAP in cancer progression might be dependent on cancer tissues and cell types." (PMID 31240993, 2019). "In the cancer metastasis that is mediated by the interaction between X-linked inhibitor of apoptosis (XIAP) and survivin but independent of inhibition of cell death, FN expression serves a downstream signaling factor to promote the metastasis process." (PMID 31861892, 2019). "Moreover, it has been reported that XIAP and Smac are negatively correlated in various cancers such as renal cell carcinoma and non-small cell lung cancer." (PMID 31699976, 2019). "XIAP diminishes anti-cancer agents-induced apoptosis via inhibition of caspase-3 activation." (PMID 31238539, 2019). "Furthermore, recent studies have shown a novel role of XIAP in regulating cancer cell motility varies upon cancer types." (PMID 31548877, 2019). "Upregulation of XIAP in human cancers has been correlated with a poor prognosis." (PMID 31310659, 2019). "Additionally, pharmacological XIAP antagonization should be further evaluated in preclinical studies to evaluate its potential as targeted cancer therapy." (PMID 31151416, 2019). "In many cancer studies, NF-κB-mediated drug resistance is through up-regulation of XIAP." (PMID 31383789, 2019). "Indeed, XIAP specific inhibitors such as Embelin, Mithramycin A are able to overcome the DL resistance in different cancer types." (PMID 31553717, 2019). "Interestingly, secretions from the cancer microenvironment can provide protection to cancer cells against apoptosis by modulating XIAP levels." (PMID 31652965, 2019). "Moreover, the remaining two targets, CAV and XIAP, have been found to be involved in cancer pathogenesis." (PMID 30894171, 2019). "Interestingly, H-scores of β-catenin were also found to follow similar trends with H-scores of p68 and NF-κB target genes-Bcl-2, Bcl-xL, Survivin and XIAP in both normal and carcinoma samples." (PMID 31351496, 2019). "XIAP inhibits both caspase-9 and -3, leading to suppression of apoptosis within cancer cells." (PMID 29522451, 2018). "CpdA could significantly decrease expressions of IL-6, XIAP and IL-8, as well as excreted IL-8 levels together with reduced cancer viability after PTX treatment." (PMID 29486738, 2018). "In contrast, IL-6, IL-8 and XIAP levels were reduced in TLR4-knockdown cancer cells." (PMID 29486738, 2018).
cancer (continued). "The NF-κB activation of XIAP is essential for cancer cell survival." (PMID 29772677, 2018). "TLR4 ligation by PTX could activate downstream signaling via NF-κB and MAPK that promote pro-inflammatory mediators i.e. IL-6, IL-8, MCP-1, VEGF and XIAP, the functions of which have been reported to enhance cancer progression and drug resistance." (PMID 29486738, 2018). "In addition, several reports have indicated that XIAP of cancer cells imparts TRAIL-resistance, and CQ reduced XIAP expression in both cell lines." (PMID 29513749, 2018). "In addition, with this pathway, the anti-apoptotic protein XIAP is induced in cancer cells leading to the anti-apoptotic response to PTX." (PMID 29486738, 2018). "Importantly, genetically forced expression or silencing of survivin, Mcl-1, XIAP, or cIAP2 in cancer cells, respectively, demonstrated their roles in mediating the action of FL118." (PMID 30285798, 2018). "Our study reveals a novel regulatory mechanism towards chemo-drug resistance, and suggests that XIAP may serve as a potential therapeutic target in those chemo-resistant cancer cells." (PMID 29581832, 2018). "XIAP has been proposed to inhibit cell death and enhance chemoresistance in cancer." (PMID 29486738, 2018). "Our data has shown that embelin causes a dose-dependent apoptotic cell death in leukemic cells via inducing apoptosis, supporting previous findings that small molecular inhibitors such as embelin can be used to inhibit XIAP in a variety of cancers including the induction of apoptosis." (PMID 28704451, 2017). "Whereas, decreased expression of XIAP sensitizes drug-resistance of cancer cells to apoptosis." (PMID 29221164, 2017). "Therefore, XIAP antagonism can be a powerful strategy to overcome chemo-resistance across a variety of cancers and a number of current IAP-antagonist strategies involve XIAP down-regulation or inhibition to promote cancer cell survival." (PMID 28424988, 2017). "Moreover, two genes CAV and XIAP have been involved in cancer pathogenesis including HNSCC by past studies." (PMID 28415821, 2017). "In addition, we and others have also shown that XIAP expression and activated AKT are closely associated in rendering a cancer cell resistant and aggressive." (PMID 28893228, 2017). "Researches reveal that overexpression of XIAP contribute to resistance of cancer cells to clinical chemotherapeutic drugs such as 5-FU, and thus high expression level of XIAP is responsible for poor prognosis in many cancers." (PMID 29371950, 2017). "In addition, XIAP over-expression also leads to poor prognosis in many cancers including breast and thyroid cancer." (PMID 28893228, 2017). "In the same vein, pro-survival proteins including inhibitor of apoptosis proteins (IAPs), X-linked inhibitor of apoptosis protein (XIAP) or survivin, are often highly expressed in cancer cells and may counteract TRAIL-induced apoptosis as well." (PMID 31548531, 2017). "Cisplatin treatment caused a significant increase in the expression of RIP1, cIAP1 and XIAP in the control cells, which implies that these proteins may be involved in counteracting the apoptosis effect of cisplatin in wild-type cancer cells." (PMID 28139737, 2017). "Although recent studies show the co-overexpression of XIAP and EGFR in many cancers, and the high sensitive to anti-IAPs therapy if the cancers with EGFR overexpression, a possible association of XIAP with EGFR overexpression has never been explored in previous studies." (PMID 28057023, 2017). "Recently, we reported that the FDA-approved drug disulfiram when combined with copper (DSF-Cu) enhances uptake in cancer cells and inhibits pNFκB leading to decreased XIAP, enhanced oxidative stress-induced apoptosis and significant inhibition of SUM149 tumor growth in a murine xenograft model." (PMID 28460441, 2017).
cancer (continued). "XIAP is the only member of the IAPs that has been shown to inhibit the functionality of both; the initiation caspase (caspase-9) as well as executioner caspase (caspase-3) thereby limiting the role of apoptosis in cancer cells." (PMID 28704451, 2017). "X-linked inhibitor of apoptosis protein (XIAP) is a prominent protein member of the inhibitor of apoptosis (IAP) that collectively involved inhibition of apoptosis and thereby improving the survival of cancer cell." (PMID 28704451, 2017). "Moreover, ISG15 abolishes TNF-α-activated NF-κB signaling and decreases the transcription of NF-κB-modulated genes including XIAP and Mcl-1, two oncogenes in various cancers." (PMID 27659523, 2016). "Moreover, the nanoparticles suppressed the EGFR–ERK–NF-κB signaling pathways as well as the expression of the related tumor promoting proteins MMP-9 and XIAP, and subsequently inhibited the migration and invasion capabilities of cancer cells." (PMID 27833124, 2016). "TAK1 and XIAP are potent inhibitors of apoptotic cell death in cancer cells." (PMID 27048361, 2016). "Therefore, concurrent targeting of the BIR2 and BIR3 domains in XIAP is a highly attractive strategy to antagonize IAPs and promote apoptosis in cancer cells." (PMID 27223062, 2016). "The XIAP protein level correlated with the sensitivity to multiple anti-cancer drugs." (PMID 27658583, 2016). "Furthermore, research efforts have been focused on the development of drugs targeting XIAP as a new approach to counteract cancer and overcome drug resistance." (PMID 27259577, 2016). "Therefore, it is seldom thought that survivin and XIAP play a role in SAHA-induced autophagy in cancer cells." (PMID 27065869, 2016). "However, the expression of the other phosphorylated proteins, with the exception of phospho-XIAP expression, was detected in normal and cancer tissues." (PMID 26314849, 2015). "The effects of XIAP knockdown on autophagy are modest, compared with the overexpression effects, suggesting that the major relevance of this gene in autophagy is when it is amplified in cancers." (PMID 25669656, 2015). "However, their study focussed on the effects of XIAP knockdown, while we have stressed the consequences of amplification in the cancer context, where we showed that autophagy is inhibited by embelin in cancer cells lines with XIAP amplification." (PMID 25669656, 2015). "We found that binding of XIAP IRES to the MDM2 RING domain protein inhibited its ability for self-association and self-ubiquitination, which increased MDM2 protein stabilization and cancer cell survival." (PMID 25888903, 2015). "This suggested that cancer cells that survive treatment responded by increasing their XIAP protein levels which may have resulted in radio chemotherapy resistance." (PMID 26071313, 2015). "In a nanoparticulate formulation limiting its action to αvβ3, tetrac modulates integrin-dependent effects on gene expression in human cancer cell lines that include increased expression of a panel of pro-apoptotic genes and decreased transcription of defensive anti-apoptotic XIAP and MCL1 genes." (PMID 26041883, 2015). "In cancer, both ERK and AKT signaling confer resistance to apoptosis via upregulation of a panel of anti-apoptotic proteins including MCL1, X-linked inhibitor of apoptosis protein (XIAP) and BCL-xL." (PMID 26517243, 2015). "The higher expression levels of XIAP and cIAP1 in some cancer cells may contribute to tumour maintenance not only via the inhibition of apoptosis, but also through the activation of autophagy." (PMID 25669656, 2015). "In cancer cells where XIAP is over expressed Smac levels may be insufficient to block XIAP activity, and this disturbed XIAP/Smac balance may contribute to apoptotic resistance." (PMID 26071313, 2015). "XIAP expression has previously been shown to be an important factor in cancer progression." (PMID 26071313, 2015).
cancer (continued). "In a classical approach by using antisense oligonucleotides, siRNA or morpholino-antisense, the decrease of the mRNA and protein levels of XIAP was shown to sensitize drug-resistant cancer cells to therapy-induced apoptosis or to induce even spontaneous cell death specifically in cancer cells." (PMID 25120954, 2014). "Caspase-3 could cleave XIAP in an another positive feedback loop to further sensitize cancer cells to UCN-01-induced apoptosis." (PMID 25356864, 2014). "Here, we showed that expressing XIAP with RING (Really Interesting New Gene) domain deletion (XIAPΔRING) in cancer cells promoted cancer cell anchorage-independent growth and G1/S phase transition companied with increasing cyclin e transcription activity and protein expression." (PMID 25216527, 2014). "CDKI-73 decreased XIAP and synergizes with fludarabine for cancer inhibition." (PMID 24980821, 2014). "This means that XIAP may play distinct roles in different types/subtypes of cancer and although it may serve as a biomarker for cancer tissue, targeting of XIAP in specific patient subgroups has to be carefully evaluated." (PMID 25120954, 2014). "In contrast, XIAP levels are relatively high in the majority of cancer cell lines." (PMID 24874286, 2014). "Taken together with poor clinical outcome of the cancer patients with high expression of XIAP in nuclear, our novel findings of XIAPΔRING in nuclear location and upregulation of E2F1/Cyclin E axis provide us significant insight into understanding of nuclear XIAP in cancer patients." (PMID 25216527, 2014). "ChIP experiments show that the Sp1 occupies its binding sites in the promoters of XIAP, CRABP1, MDK, and KCNMA1, and that DIG-MSK decreases Sp1 binding to them with a superior effect on KCNMA1, a gene associated with high proliferation in cancer cells." (PMID 25110883, 2014). "In addition, the current studies also provide very useful information for new drug design, which can target nuclear XIAP in cancer cells." (PMID 25216527, 2014). "Studies suggested that a high level of XIAP to XAF1 expression in cancer cells may provide a survival advantage through the relative increase of XIAP anti-apoptotic function." (PMID 24874286, 2014). "Therefore, allowing cancer cells to regain their ability to proceed to apoptosis by inhibiting XIAP is an elegant strategy to fight cancers." (PMID 24824137, 2014). "XIAP up-regulation could contribute to tumorigenicity and XIAP has been observed to be over-expressed in numerous types of cancers." (PMID 25574358, 2014). "Furthermore, the targeted inhibition of XIAP or survivin genes has been shown to directly sensitize cancer cells to apoptosis induced by various conventional chemotherapeutic drugs." (PMID 23721525, 2013). "The decreased expression of death receptors TRAIL-R1 and TRAIL-R2 and antiapoptotic proteins (Bid, Bax, Bak, Smac/DIABLO) or increased expression of antiapoptotic proteins (FLIP, Bcl-2, Bcl-xL, Mcl-1, Akt, IAP-1, IAP-2, XIAP, survivin) in cancer cells were involved in TRAIL-resistance." (PMID 23573148, 2013). "X-linked inhibitor of apoptosis protein (XIAP) is the best studied protein in the human IAP family of proteins from the standpoint of biochemical mechanism and its overexpression in several types of human cancers has been documented." (PMID 23408474, 2013). "It is also indicated that down-regulation of EMMPRIN by RNA interference could result in decreased X-linked inhibitor of apoptosis (XIAP) expression and an anti-tumor effect through enhancing the susceptibility of cancer cells to apoptosis." (PMID 23516431, 2013). "Many cancers overexpress cIAP1 and XIAP, and are addicted to their expression." (PMID 23383209, 2013). "Therefore it indicated that XIAP played a key role in mediation of cancer cell migration and invasion." (PMID 22532870, 2012).